IL6 (interleukin 6)
Diseases named in the same sentence as IL6 in open-access papers (continued):
Sharing a sentence is not in itself a finding about the gene and the disease.
COVID-19 (continued). "Given the urgent need for effective treatments for COVID-19 and the social and economic costs associated with the pandemic, we perform a systemic review of all published RCTs to answer to the unsolved question: should we use IL-6 inhibitors to treat our COVID-19 patients?" (PMID 34704175, 2021). "Our cohort consisted of 46 adult patients with PCR-proven SARS-CoV-2 infection admitted in a COVID-19 ward of the Hospital de Braga (HB) from April 7 to May 7, 2020, whose IL-6 levels were followed over time." (PMID 33679753, 2021). "TNF was barely detectable in COVID-19 serum samples and highest in individuals with moderate disease, suggesting that another cytokine, for example IL-6, or stimulus may be responsible for NF-κB activation in asymptomatic individuals with COVID-19." (PMID 33879890, 2021). "Finally, we found that cytokine levels were acutely increased in severe and critical COVID-19 patients, particularly IL-6, IL-10, CRP and PCT." (PMID 33735325, 2021). "It is possible that common pathways such as IL-6 could trigger and aggravate dilated cardiomyopathy in pregnant women who develop COVID-19 in peripartum period, and COVID-19 prevention might be more important in this period." (PMID 33741059, 2021). "While Tocilizumab may be used to treat COVID-19, it may promote a secondary coinfection, such as aspergillosis, as it functions to reduce serum IL-6 levels." (PMID 34940403, 2021). "Another complementary study has not only confirmed that severe COVID-19 patients display significantly higher plasma levels of IL-6, IL-10, and TNF-α than mild cases but also demonstrated a negative correlation between the plasma concentration of these cytokines and the recovery phase." (PMID 34209845, 2021). "Tocilizumab is approved for use in patients with COVID-19 as it is a potent IL-6 inhibitor." (PMID 34940403, 2021). "Although only scarce evidence is available on other Th cell subsets in COVID-19 cases to date, higher blood plasma levels of anti-inflammatory IL-6 and IL-10 related to Th2 subsets, and lower Treg, were reported to be associated with patients requiring intensive care in the hospital." (PMID 33808906, 2021). "It was also observed that patients with severe COVID-19 had higher levels of IL-6." (PMID 34680795, 2021). "In addition to the chemokines MCP-1/CCL2 and MIP-1α/CCL3, which were increased in COVID-19 patients, IL-6 and TNF-α production also depends on NF-κB activation." (PMID 33232303, 2021). "Therefore, some authors recommended the use of tocilizumab in critical COVID-19 cases with significantly elevated IL-6." (PMID 34063964, 2021). "Notably, it was also observed that severe COVID-19 patients had increased levels of angiotensin II and IL-6." (PMID 34285712, 2021). "The immunopathological mechanisms of the severe acute respiratory syndrome coronavirus 2 (SARS-CoV-2) infection include rising levels of several cytokines and in particular IL-6." (PMID 33530554, 2021). "In COVID-19 patients, IL-6 levels appear to be directly related to disease severity." (PMID 34001199, 2021). "Plasma profiling identified multiple features shared by MIS-C, Kawasaki Disease and COVID-19 and that therapeutic inhibition of IL-6 may be preferable to IL-1 or TNF-α." (PMID 34632327, 2021). "Another advantage of using CAR-NK cell-based therapy is that NK cells produce minimal proinflammatory cytokine IL-6, which has been shown to significantly contribute to the cytokine release syndrome (CRS) that is caused by CAR-T immunotherapy or observed in severe COVID-19 patients." (PMID 34367128, 2021). "Sarilumab and Siltuximab are interleukin-6 (IL-6) inhibitors implied for the treatment of rheumatoid arthritis and Castleman disease, respectively, and can be used in the management of cancer patients with COVID-19." (PMID 33912588, 2021).
COVID-19 (continued). "Of all the upregulated cytokines that may represent selective therapeutic targets, IL-6 has been regarded as particularly important in the COVID-19 pathogenesis and may be antagonized by existing drugs." (PMID 33679753, 2021). "The expression of these submodules in the blood transcriptome of this small number of COVID-19 patients revealed variation in IL-1β and IL-6 bioactivity over the period of hospitalization, with higher expression seen earlier during hospital admission and a reduction as patients recovered." (PMID 33319166, 2021). "We then compared the performance characteristic of progranulin as a biologic marker for the differentiation between sepsis, the systemic inflammatory response to major surgery, bacterial pneumonia and COVID-19 to that of the established indicators procalcitonin, interleukin-6 and C-reactive protein." (PMID 34476621, 2021). "Patients with COVID-19 have elevated levels of various cytokines such as IL-2, IL-4, IL-6, and IL-10, TNF-α, IFN-γ and may present with the so-called cytokine storm." (PMID 34684384, 2021). "Therefore, clarification of the appropriate patient population eligible for tocilizumab monotherapy or its combination with corticosteroids and the positioning of IL-6 inhibitors in COVID-19 treatment are of great importance." (PMID 34631752, 2021). "The majority of the COVID-19 patients exhibited preexisting comorbidities which include cardiovascular, respiratory, and renal disorders accompanied by a severely low level of vitamin D, extremely high level of IL-6, and low glomerular filtration rate (eGFR)." (PMID 34576798, 2021). "Lymphopenia, thrombocytopenia and higher levels of IL-6, ferritin, D-dimer, aspartate aminotransferase, lactate dehydrogenase, CRP, procalcitonin, creatinine, neutrophils and leukocytes were associated with severe and fatal cases of COVID-19." (PMID 34185801, 2021). "Consistent with previous reports, we found that severe COVID-19 was characterised by elevated IL6." (PMID 33704068, 2021). "It is suggested that if the level of IL-6 is consistently high, clinical outcomes could be worse; therefore, close observation is needed from the time of initial diagnosis of COVID-19." (PMID 34575353, 2021). "ApoA-1 and HDL levels were shown to be negatively correlated with CRP and IL-6 levels in patients with COVID-19, suggesting that the increased inflammatory response related to reduced HDL levels is one of the pathogenic mechanisms of COVID-19." (PMID 34335279, 2021). "Interestingly, B cells from patients with acute COVID-19 displayed an IL-6/IL-10 cytokine imbalance in response to Toll-like receptor activation, skewed toward a pro-inflammatory phenotype." (PMID 33821250, 2021). "Severe COVID-19 patients showed higher serum concentrations of IL-6 than mild and control groups." (PMID 34831404, 2021). "However, in COVID-19 patients, significantly higher contribution of IL-6-producing cells came from Mo-MDSC and PMN-MDSC." (PMID 33692788, 2021). "At a cut-off of 35 pg/ml, IL-6 effectively differentiated COVID-19 patients who received mechanical ventilation, with a sensitivity of 95.2% (95% CI 77.3 – 99.2), specificity of 56.8% (95% CI 42.2 – 70.3), PPV of 51.3% (95% CI 36.2 – 66.1) and NPV of 96.2% (95% CI 81.1 – 99.3)." (PMID 34781995, 2021). "Indeed, serum levels of IL-6 positively correlate with the severity of COVID-19 75, 77, 78 and also predict the mechanical ventilation need for COVID-19 patients." (PMID 33907513, 2021). "In parallel, a critical reduction of IL-1β, IL-1RA, IL-6, and TNF-α concentration was evident 2 days after MSC infusion, mimicking the effectiveness of other immunomodulatory agents, such as baricitinib, in dampening COVID-19-associated inflammation." (PMID 34078447, 2021).
COVID-19 (continued). "Moreover, endothelial homeostasis acts as a gatekeeper of immune responses, as the inhibition of IL-6 trans-signaling in endothelial cells dampens the propagation of cytokine storms associated with sepsis, ARDS, burns, and severe cases of COVID-19." (PMID 34253862, 2021). "Activated T-cells secrete colony-stimulating granulocyte macrophages (GM-CSF) and in turn by chemotaxis recruit monocytes with strong pro-inflammatory potential through excessive secretion of IL-6, phenomena that will correlate with severe lung disease in some patients with COVID-19." (PMID 34066560, 2021). "Since tocilizumab, an antibody against the IL-6 receptor, is one of the most effective drugs for patients with severe COVID-19, we also demonstrated that the levels of both secreted and dimeric intracellular IL-6 were increased in response to both RBD and H2O2 and decreased by CO2." (PMID 34741187, 2021). "More notably, we observed that the elevation of IL-6 before the aggravated pulmonary lesions in the majority of COVID-19 patients; thus, we speculated that IL-6 might serve as a driving factor for pulmonary pathogenesis during SARS-CoV-2 infection." (PMID 33390771, 2021). "Novel anti-inflammatory approaches, such as the antagonists for IL-6 or IL-1β signaling, in addition to antithrombotic treatments, might have a greater effect in preventing thrombosis and death in COVID-19 than either therapy alone." (PMID 34768445, 2021). "This typically occurs in subjects with ARDS, where the exacerbated CRP increase and hyper ferrfitinemia are key for diagnosing MAS and are elevated in many serious cases of pneumonia due to COVID-19.The low survival rate of ARDS has been related to a sustained elevation of IL-6 and IL-1." (PMID 33776561, 2021). "A clinical study found that COVID-19 patients without other comorbidities but diabetes that had higher serum levels of inflammation-related biomarkers such as IL-6 were susceptible to a cytokine storm, leading to rapid deterioration of COVID-19." (PMID 33553435, 2021). "CRP and IL-6 are inflammation-related biomarkers that have moderate-to-high correlation with the NLR, and these biomarkers are also associated with the unfavorable aspects of COVID-19 and duration of hospitalization." (PMID 33726485, 2021). "Indeed, recent studies provided data in favor of improved outcome in critically ill patients with COVID-19 receiving IL-6 antagonists, while other studies produced mixed results." (PMID 34960725, 2021). "This may be particularly important in the pathogenesis of COVID-19 given the purported crucial role that interleukin-6 plays in some initial reports of adverse outcomes related to COVID-19." (PMID 34862487, 2021). "In addition, from the analysis of cytokines in our patients we identified a subgroup, called COVID-plus, including COVID-19-positive patients who presented much higher levels of IL-6, TNF-α, IL-1β, and CD25 than other groups." (PMID 34578450, 2021). "IL-6 inhibitors reduced longest follow-up mortality and intubation in COVID-19 patients." (PMID 34704175, 2021). "Our results also suggest management of proinflammatory cytokines other than IL-6 may help toward recovery from severe COVID-19, as evidenced by the consolidated benefit of low-dose corticosteroid in treatment." (PMID 34199240, 2021). "The hematological profile of a patient typically affected with coronavirus disease 2019 (COVID-19) showed lymphopenia with an altered neutrophil-lymphocyte ratio, raised inflammatory markers like D-dimer, interleukin 6 (IL-6), C-reactive protein (CRP), lactate dehydrogenase, and serum ferritin." (PMID 34966605, 2021). "In COVID-19-induced CS, IL-6 is the main cytokine involved in ALI and ARDS development." (PMID 34124187, 2021). "Interestingly, it has been reported that the non-serotonergic anti-inflammatory effect of FLX potentially has the ability to inhibit IL-6 and NF-κB signaling pathways driving the cytokine storm in COVID-19." (PMID 33572117, 2021).
COVID-19 (continued). "In COVID-19, IL-6 has been positively correlated with disease stages and radiologic changes." (PMID 33679753, 2021). "Annexins have been found in various animal models to reduce the levels of IL-6, so there may be potential for its use in treatment of COVID-19 inflammation as an adjunct or alternative approach to anti-IL-6 receptor antibodies." (PMID 34566657, 2021). "Accordingly, BTK inhibitors may regulate inflammatory responses in COVID-19 by reducing the levels of IL-6." (PMID 34001144, 2021). "Therefore, at the time of enrolment different COVID-19 outcome groups were identifiable based on distinct patterns of inflammatory mediators; IL-6, CXCL10, and GM-CSF were key determinants of cluster assignment." (PMID 33692097, 2021). "This has also been shown on COVID-19 lung autopsies, where alveolar macrophages expressing IL-6 and MCP-1 found in the lung tissues, leading to endothelial damage and necrosis that were evidenced by IL-6 secreting macrophages and ECs adhering to vascular thrombi." (PMID 34372552, 2021). "Previous studies reported that COVID-19 is frequently associated with a massive production of 14 cytokines including IFN-γ, IL-1RA (IL1RN), IL-2RA, IL-6, IL-10, IL-18, HGF, MCP-3 (CCL7), MIG (CXCL9), M-CSF (CSF1), G-CSF (CSF3), MIG-1a (CCL3), CTACK (CCL27), and IP-10 (CXCL10)." (PMID 34262555, 2021). "Many of the studies are under consideration explaining the mechanism of IL-6 in COVID-19." (PMID 35004038, 2021). "Indeed, IL-6 plasma levels in COVID-19 severe patients are 10- to 40-fold lower than previously reported ARDS patients, and 1000-fold lower compared with patients facing cytokine release syndrome following treatment with chimeric antigen receptor T cells." (PMID 33674591, 2021). "In COVID-19, serum concentrations of proinflammatory cytokines, including IL-2, IL-6, and tumor necrosis factor (TNF)-a, were markedly increased in severe cases than moderate cases, suggesting that cytokine storms could be associated with disease severity." (PMID 34903765, 2021). "In hospitalised COVID-19 patients, DN2 cells are associated with high neutralising antibody titres and elevated plasma concentrations of inflammatory biomarkers, such as CRP, CXCL10, and IL-6." (PMID 34964023, 2021). "Moreover, tocilizumab, an interleukin-6 antagonist, was used in a substantial proportion (56%) of patients with severe COVID-19." (PMID 33481096, 2021). "M-MDSCs have been found accumulated in severe COVID-19 patients, and they seem to have been responsible for the production of IL-6 in these patients, whereas others have found that G-MDSCs may predict fatal COVID-19 outcomes." (PMID 35154077, 2021). "IL-6 may be considered one of the key factors for the subsequent evolution of COVID-19 among hospitalized patients." (PMID 34829949, 2021). "Similarly, a retrospective observational study in hospitalised patients diagnosed with COVID-19 showed that serum levels of IL-6 greater than 30 pg/mL was a predictor of invasive mechanical ventilation requirement." (PMID 33860869, 2021). "The authors of the study concluded that homogenous hyperinflammatory innate immune responses (higher plasma concentrations of TNF-α and IL-6) in COVID-19 patients are combined with defective adaptive immune responses due to profound lymphopenia, exhausted T cells and decreased functionality." (PMID 34945111, 2021). "We measured the angiotensin II and IL-6 levels of COVID-19 patients who were administered ARBs." (PMID 34285712, 2021). "Tumor necrosis factor-α (TNF-α) and interleukin 6 (IL-6) production by circulating monocytes is sustained in severe COVID-19 patients but not in bacterial sepsis or influenza-associated cytokine storms in which the monocyte numbers and function are impaired." (PMID 33672738, 2021).
COVID-19 (continued). "The complicated immunopathological phenomena observed in severe COVID-19 patients, such as massive macrophages and neutrophils infiltration, and excessively increased proinflammatory cytokines such as IL-6, were also observed in this MASCp36-infected mouse model." (PMID 34580297, 2021). "As a result of this, the elevated levels of IL-6 observed in cancer patients and survivors can exacerbate the effect of a potential COVID-19-mediated cytokine storm in infected patients also through IL-6, which can lead to increased injury in both lung and myocardial tissue." (PMID 33969006, 2021). "Moreover, the relative expression of IL-6 in severe COVID-19 patients was the highest in Mo-MDSCs, as compared to the relative expression of IL-6 in monocytes and PMN-MDSC." (PMID 33692788, 2021). "Importantly, median IL-6 serum levels are one or two magnitude order lower in COVID-19 compared to fully blown cytokine storm syndromes, thus supporting that a differential pathogenic scenario is plausible, distinct from the classical cytokine storm framework." (PMID 33669218, 2021). "A noticeable meta-analysis of the anti-inflammatory capacity of melatonin administration has recently confirmed, based on 13 studies and a global cohort of 749 people, the reduction of TNF-α and IL-6 levels, suggesting that it would have a similar effect on COVID-19 patients." (PMID 34356384, 2021). "This different and dynamic change in IL-6 and IL-10 levels, especially the decrease in the serum levels in the survivor group, has led to the clarification of the predictive role of cytokines on the prognosis of COVID-19 with prospective follow-up." (PMID 34855834, 2021). "In addition, elevated CD14+CD16+ inflammatory monocytes producing high levels of IL-6 are found in COVID-19 patients, suggesting that also monocytes actively contribute to the systemic inflammatory response." (PMID 33839767, 2021). "Blocking the cytokine IL-6 axis is a promising therapy for patients developing COVID-19 pathology." (PMID 34909094, 2021). "Therefore, it was recommended to restrict the tocilizumab treatment to patients with high IL-6 levels (“WHO R&D Blueprint COVID-19 Informal Consultation on the Potential Role of IL-6/IL-1 Antagonists in the Clinical Management of COVID 19 Infection” 2020)." (PMID 34012390, 2021). "Patients with severe COVID-19 show increased IL-2, IL-6, IL-7, granulocyte colony-stimulating factor (G-CSF), interferon-γ-inducible protein 10 (IP-10), monocyte chemoattractant protein 1 (MCP-1), macrophage inflammatory protein 1-α (MIP-1), and tumor necrosis factor-alpha (TNFα)." (PMID 35062245, 2021). "Yet, severe lymphopenia and T cell exhaustion may worsen the condition of the COVID-19 patients who are treated with IL-6 blocking agents." (PMID 34945111, 2021). "The link between IL-6, Lp(a), and COVID-19 is of interest, particularly in view of studies addressing whether tocilizumab suppresses symptoms and complications associated with COVID-19." (PMID 34033878, 2021). "Accordingly, in this current study, we assessed and compared the vitamin D, IL-6, and eGFR levels in serum obtained from three different groups, namely a COVID-19 patients group (PP n = 80) and a healthy (NNp n = 62) group and non-healthy (NNh n = 43) group used as controls (total n = 185)." (PMID 34576798, 2021). "A metabolite panel made of kynurenine/tryptophan ratio, IL-6, LysoPC a C18:2, and phenylalanine discriminated non-COVID-19 from sepsis patients with an area under the curve (AUC (95%CI)) of 0.991 (0.986–0.995), with sensitivity of 0.978 (0.963–0.992) and specificity of 0.920 (0.890–0.949)." (PMID 34460840, 2021). "Our study showed that a high level of IL-6 was a predictor of death in severe COVID-19 patients." (PMID 33731184, 2021). "Current international guidelines suggest that IL-6 inhibitors might have therapeutic value if implemented in severely ill COVID-19 patients." (PMID 33714258, 2021).